MIR4653 (microRNA 4653)
Synonyms: hsa-mir-4653
Gene: MicroRNA gene on chromosome 7 (101,159,473 to 101,159,555, forward strand). Ensembl gene ENSG00000264425.
Homologues: Orthologues: chimpanzee MIR4653 (100% identical).